GSTP1 (glutathione S-transferase pi 1)
Diseases named in the same sentence as GSTP1 in open-access papers (continued):
Sharing a sentence is not in itself a finding about the gene and the disease.
gastric cancer (continued). "We evaluated the interaction between GSTP1 Val allele and Helicobacter pylori infection, smoking and alcohol consumption, increasing the risk of gastric cancer among the Chinese population." (PMID 23077566, 2012). "We further evaluated the association between the genotypes of GSTP1 and risk of gastric cancer and its precancerous conditions by subgroups of age, sex, H. pylori infection, smoking status, and alcohol consumption." (PMID 23077566, 2012). "Regarding gastric cancer, only a few studies were conducted to investigate its association with GSTP1 variants." (PMID 23077566, 2012). "The risk of gastric cancer was significantly elevated in patients with the GSTP1 Val/Val genotype (adjusted OR = 3.324; 95% CI = 1.790–6.172)." (PMID 23077566, 2012). "In our study, the GSTP1-105 polymorphism was identified as a predictive and a prognostic marker in gastric cancer patients." (PMID 16317430, 2006). "Our findings indicate that dietary ORAC intake may be inversely associated with the risk of gastric cancer altered by genetic variants of GSTP1, providing new intervention strategies for gastric cancer patients." (PMID 33634021, 2020). "In this study, we aimed to determine whether an antioxidant-rich diet is associated with gastric cancer risk and identify how this association could be altered by GSTP1 genetic variants." (PMID 33634021, 2020). "Association of the GSTP1 Val/Val genotype with smoking or alcohol consumption could significantly increase atrophic gastritis and gastric cancer risk." (PMID 23077566, 2012). "To examine whether the risks of gastric cancer and its precancerous conditions were related to GSTP1 genotype, we analyzed the association between GSTP1 genotype and the risk of atrophic gastritis and gastric cancer." (PMID 23077566, 2012). "Moreover, the combined effect of GSTP1 Val allele with environmental carcinogens (H. pylori infection, smoking, and alcohol consumption) significantly increases the risk of gastric cancer development." (PMID 23077566, 2012). "Association of the GSTP1 Val/Val genotype with H. pylori IgG(+), smoking, or alcohol consumption could significantly increase atrophic gastritis and gastric cancer risk." (PMID 23077566, 2012). "In conclusion, our results suggest that polymorphism of GSTP1 may contribute to gastric cancer susceptibility in the Chinese population." (PMID 23077566, 2012). "Stratification analysis of association between GSTP1 genotype and gastric cancer risk." (PMID 23077566, 2012). "An elevated risk of gastric cancer was observed in patients with H. pylori infection, smoking, or alcohol consumption, and together with the GSTP1 Ile/Val +Val/Val genotype (OR = 3.696; 95% CI = 2.475–5.521; OR = 1.638; 95% CI = 1.044–2.571; OR = 1.641; 95% CI = 0.983–2.739, respectively) (p<0.05)." (PMID 23077566, 2012). "This important finding suggests that GSTP1 genotyping and H. pylori IgG seropositivity could be used to identify individuals with a high risk of gastric cancer and its precancerous conditions." (PMID 23077566, 2012). "Testing for TS and GSTP1 polymorphisms may allow identification of gastric cancer patients who will benefit from 5-FU/cisplatin chemotherapy, sparing others the side effects of this chemotherapy." (PMID 16317430, 2006). "To conclude, this pilot study demonstrated that combined genotype analysis of GSTP1, TS-5′ 28bp and TS-5′ G → C polymorphisms may contribute to the selection of gastric cancer patients who would benefit most from 5-FU/cisplatin combination chemotherapy." (PMID 16317430, 2006). "Association between dietary oxygen radical absorbance capacity (ORAC) intake and gastric cancer (GC) risk by rs1871042 polymorphism of GSTP1 gene." (PMID 33634021, 2020). "Association between tag single nucleotide polymorphisms (SNPs) of GSTP1 gene and gastric cancer (GC) risk." (PMID 33634021, 2020).
gastric cancer (continued). "A variant of GSTP1 has a lower efficiency for most of the environmental carcinogens (e.g. H. pylori infection, smoking, and alcohol consumption) that may cause some individuals’ susceptibility to gastric cancer and its precancerous conditions." (PMID 23077566, 2012). "Conversely, it has been found that the genotype GSTP1 A/A is predicted to show a suboptimal response to chemotherapy with fluorouracil/cisplatin, and a lower survival rate in patients with advanced gastric cancer." (PMID 30914949, 2019). "GSTP1 A/A genotype has been found to predict suboptimal response to flurouracil/cisplatin chemotherapy and poor survival in patients with advanced gastric cancer." (PMID 25452763, 2014). "We found that there was a significant difference in the GSTP1 polymorphic types between the gastric cancer cases and superficial gastritis controls." (PMID 23077566, 2012). "We investigated the interaction between GSTP1 genotype and H. pylori infection in gastric cancer and its precancerous conditions." (PMID 23077566, 2012). "The frequency of GSTP1 Val/Val genotypes was significantly higher in the gastric cancer group, compared with Ile/Ile or Ile/Val genotypes." (PMID 23077566, 2012). "High prevalence of GSTP1 gene methylation has been found in the serum of gastric cancer patients." (PMID 31357662, 2019). "Despite this, with the data presented we can conclude that the GSTP1 polymorphic allele and the GSTM1 and GSTT1 null alleles appear to result in enhanced overall survival and progression free survival, particularly in gastric cancer where the data have been more consistent." (PMID 25452763, 2014). "Therefore, we looked for interaction between GSTP1 genotype and H. pylori IgG, smoking, or alcohol consumption in gastric cancer and its precancerous conditions." (PMID 23077566, 2012). "Researchers in the USA have reported that the GSTP1 genotype seemed not to be associated with the risk of gastric cancer and chronic gastritis in a high-risk Chinese population." (PMID 23077566, 2012). "This suggests that individuals from Northern China with GSTP1 allele Val have an increased risk of gastric cancer, but not atrophic gastritis (one of the precancerous conditions)." (PMID 23077566, 2012). "The mechanism of the association between GSTP1 gene polymorphism and gastric cancer was not clear in our study." (PMID 23077566, 2012). "Moreover, patients with GSTP1 Val/Val genotypes were associated with risk of gastric cancer in almost all subgroups except for non-smoking or non-alcohol consumption subgroups (adjusted OR and 95% CI)." (PMID 23077566, 2012). "Recurrent gastric cancer patients with ERCC1 rs3212964, ERCC1 rs2298881, or GSTP1 rs1695 SNPs had higher ERCC1 expression and had a worse OS." (PMID 39516666, 2024). "GSTP1 interacts with Jun N-terminal kinase (JNK) and inhibits apoptosis in lung cancer cells and gastric cancer cells." (PMID 34209254, 2021). "CpG hypermethylation of GSTP1 is an epigenetic modification which is commonly found in EBV related gastric cancer (20%), but rare (0.4%) in EBV-negative gastric cancer." (PMID 32899442, 2020). "Recently a study confirmed CLDN23 as a potential biomarker for the diagnosis and prognosis of gastric cancer, and it was further demonstrated that CLDN23 expression was positively correlated with GSTP1 activity in gastric cancer." (PMID 29116019, 2017). "While GSTP1 and PTEN promoters remained unmethylated in both neoplastic and non-neoplastic gastric epithelia, TSLC1 promoter hypermethylation is highly cancer specific, but is observed at only a low frequency in gastric cancer." (PMID 15138487, 2004). "These cytokines that could not be detoxified by GSTP1 could directly induce gastric mucosal damage and eventually lead to development of atrophic gastritis and even gastric cancer." (PMID 23077566, 2012).
bladder cancer (25 papers, 2009 to 2025). "Another study involving 7236 patients with bladder cancer identified that the GSTP1 gene 313 A/G (rs1695) polymorphism increased the risk of bladder cancer development." (PMID 39336970, 2024). "We also attempted to evaluate the clinical significance of HER2 status in cases confirmed to have GSTM1/ GSTP1 variants with bladder cancer prognosis." (PMID 31646988, 2019). "Polymerase chain reaction-based and Sanger gene sequencing-base assays were undertaken to assess the contribution of genetic polymorphism in GSTM1 and GSTP1 to the susceptibility of bladder cancer." (PMID 31646988, 2019). "In the present study, we aim to investigate the prognostic value of GSTM1 and GSTP1 genetic polymorphisms in patients with bladder cancer and evaluate their association with patients’ clinicopathological parameters." (PMID 31646988, 2019). "A significantly reduced risk of bladder cancer recurrence was found in patients simultaneously carrying the GSTP1 AA and GSTO1 CC genotypes, when compared to patients carrying other combinations of genotypes (HR = 0.21, 95% CI = 0.08–0.56)." (PMID 26354850, 2015). "A recent study by Pljesa-Ercegovac and coworkers revealed that high GSTP1 expression is associated with an altered apoptotic pathway and bladder cancer progression." (PMID 24252461, 2013). "A previous study by Kwabi-Addo and colleagues on non-tumor prostate tissue, obtained from organ donors and patients who underwent cystoprostatectomy for bladder cancer, found that methylation of selected genes (including GSTP1) was positively associated with the patient’s age." (PMID 31666119, 2019). "The hypothesis that GSTP1 variants modulate the risk of urinary bladder cancer has also been investigated." (PMID 31646988, 2019). "However, a slight high frequency, approximately 80%, of GSTP1 AA/AG variants was observed in in the Caucasian population with bladder cancer." (PMID 31646988, 2019). "The GSTP1 Ile105Val polymorphism has been widely investigated as a risk biomarker for various cancers, such as chronic myeloid leukemia, esophageal cancer, and bladder cancer, among others." (PMID 28410197, 2017). "Polymorphisms: GSTO2*N142D (A424G; rs156697) and other GSTs (GSTP1, GSTM1, GSTT1, GSTZ1)Main findings:- positive association between GSTO2*N142D variant and bladder cancer risk independently of arsenic exposure." (PMID 40724836, 2025). "In our investigation we examined the frequency of GSTP1 and GSTM1 variants in a cohort of 93 bladder cancer patient from Saudi Arabia." (PMID 31646988, 2019). "In the same context and for the first time we investigated the relationship between different GSTP1/GSTM1 variants and Human Epidermal growth factor Receptor 2 (HER2) gene/ protein status in bladder cancer patients." (PMID 31646988, 2019). "On the contrary, GSTP1 arrests bladder cancer T24 cells in G0/G1 phase and upregulates p21 expression." (PMID 31024008, 2019). "Genotyping of GSTM1 and GSTP1 in bladder cancer patients was assessed using polymerase chain reaction followed by DNA sequencing." (PMID 31646988, 2019). "We also evaluated the association between GSTP1 and GSTM1 gene polymorphisms with a set of clinical and pathological parameters as well as the prognostic value of both genes polymorphisms in bladder cancer patients." (PMID 31646988, 2019). "Previous studies have investigated the relationship between GSTA1, GSTM1, GSTP1, and GSTT1 polymorphisms and bladder cancer (BCa) susceptibility, respectively, but the results remain inconsistent." (PMID 27631264, 2016).
bladder cancer (continued). "In the present study, we investigated the possible association between SNPs in the GSTP1, GSTO1, GSTO2, and ABCB1 genes with response to treatment in patients with bladder cancer." (PMID 26354850, 2015). "Mutations in DNA repair genes (XRCC3) and variants in genes coding for xenobiotic-transforming enzymes (NAT2, GSTM1, GSTP1 and NQO1) have been shown to modify the susceptibility to bladder cancer." (PMID 19755987, 2009). "miR‐133a induced apoptosis through direct regulating of GSTP1 in bladder cancer." (PMID 27465833, 2016). "In this study, we aimed to determine the expression status of GSTP1 in relation to its gene promoter methylation in Moroccan population of 30 bladder cancer (BC) patients and in two noncancerous bladder tissues used as controls." (PMID 30043549, 2018).
glioma (21 papers, 2010 to 2026). A benign or malignant brain and spinal cord tumor that arises from glial cells (astrocytes, oligodendrocytes, ependymal cells). "The GSTP1 Ile105Val variant increases overall glioma risk; GSTP1 Ala114Val and GSTT1 null/present variants are shown to increase the risk of glioma in Caucasian people, but not in the Asian population." (PMID 36307808, 2022). "For instance, GSTP1 gene Ile105Val polymorphism is involved in the development of glioma and prostate cancer and other cancers." (PMID 33087132, 2020). "The GSTP1 Ala114Val carriers were associated with an increased risk of glioma in the overall population (OR=1.163(1.002- 1.350); P=0.047) and in the Caucasian population (OR=1.215(1.001-1.476); P=0.049)." (PMID 31528233, 2019). "In the literature review and analysis undertaken in this study, there were several publications on that showed an association with GSTP1 variants and the risk of glioma 1, 2, 38-40." (PMID 31528233, 2019). "Our meta-analysis confirmed that the GSTP1 Ile105Val variant was associated with an overall increased glioma risk." (PMID 31528233, 2019). "There were 7 publications that included 3,265 glioma patients and 1,273 healthy controls that included the GSTP1 Ile105Val variant dominant model (Val carriers vs. Ile/Ile)." (PMID 31528233, 2019). "Previous case-control studies assessed the association with GSTP1 polymorphisms and the risk of developing glioma, but the reported findings have been inconsistent." (PMID 31528233, 2019). "There were 5 publications including 2,342 glioma patients and 3,203 healthy controls included in the publications that included the GSTP1 Ala114Val polymorphism dominant model (Val carriers vs. Ala/Ala)." (PMID 31528233, 2019). "In humans, two non-synonymous SNPs in the electrophile-binding region of GST Pi 1 (GSTP1) isolated from malignant gliomas appear to be associated with reduced GSTP1-related enzyme activity compared to normal glioma tissue." (PMID 23613737, 2013). "However, meta-analysis undertaken in this study showed that GSTP1 Ala114Val (rs1138272) was associated with the risk of glioma in the overall population and Caucasian population studied." (PMID 31528233, 2019). "Some studies combined subtypes of glioma to analyze the distribution of GSTP1 gene polymorphisms." (PMID 31528233, 2019). "In a study on glioma, it was shown that CEBPB is associated with the expression of NQO1 and GSTP1 and can regulate the expression of antioxidant enzymes to regulate oxidative stress and mediate tumor growth in the brain." (PMID 38710698, 2024). "The JNK pathway has been found to interact with multiple GST enzymes, including GSTP1, and these interactions have been shown to promote apoptosis in glioma." (PMID 36291099, 2022). "It has been reported that serine phosphorylation of GSTP1 by PKCα enhances GSTP1-dependent cisplatin metabolism and resistance in human glioma cells." (PMID 33087132, 2020). "GSTP1 (Ile105Val and Ala114Val), GSTM1 (null/present) and GSTT1 (null/present) variants were genotyped in 384 glioma patients and 340 healthy controls." (PMID 31528233, 2019). "At this time, there have been several previously published and formally analyzed systematic reviews and meta-analysis of published studies on the GSTP1, GSTM1 and GSTT1 variants and the risk of primary brain tumors, including glioma 1, 2, 38-40." (PMID 31528233, 2019). "The study was supported by meta-analysis on GST gene variants and cerebral glioma in the Han Chinese population, which showed that GSTP1 Ile105Val and GSTT1 null/present variants were associated with the risk of glioma." (PMID 31528233, 2019). "According to the GSTP1 Ile105Val recessive model (Val/Val vs. Ile carriers), the pooling ORs of eight publications including 4,128 glioma patients and 2,134 healthy controls showed a significant association." (PMID 31528233, 2019). "Overexpression of GSTP1-1 is involved in poor prognosis in brain tumors including glioma and glioblastoma." (PMID 31357662, 2019).
glioma (continued). "Human glutathione S-transferase P1 (GSTP1) is highly expressed in many human cancers including gliomas." (PMID 21060779, 2010). "It was demonstrated that the 105G-114C (Val-Ala) haplotype of GSTP1 has a weak protective effect on the chance of developing glioma." (PMID 22649665, 2010). "GSTP1 was the key target gene of bioA; its high expression was related to poor prognosis, and its knockout could inhibit glioma progression." (PMID 42093975, 2026). "The relative risk of death in tumor patients was 3.2 times that of patients with low GSTP1 expression, and the relative risk of death in patients with GSTP1 expression in glioma nuclei was 3.9 times that in patients without GSTP1 expression in the nucleus." (PMID 36589232, 2022). "In the meta-analysis in this study, a significant association was found between GSTP1 Ile105Val (Val/Val vs. Ile carriers) and glioma risk in the Han Chinese population, but not in the Caucasian or mixed population." (PMID 31528233, 2019). "A meta-analysis of 11 case-control studies with 2,404 glioma cases and 6,379 control subjects found that the risk of glioma significantly increased between the GSTP1 A114V genotype and other histopathological gliomas, not including glioblastoma multiforme." (PMID 25013509, 2014). "Therefore, the aim of this case-control study was to investigate the relationship between GSTP1 (Ile105Val and Ala114Val), GSTT1 (null/present) and GSTM1 (null/present) variants and the risk of glioma in the Han Chinese population compared with the Caucasian population." (PMID 31528233, 2019). "Moreover, our meta-analysis also confirmed the GSTP1 Ala114Val and GSTT1 null/present variants were associated with an increased glioma risk in the Caucasian population, rather than the Asian population." (PMID 31528233, 2019).